TSC2 (TSC complex subunit 2)
Description:
Catalytic component of the TSC-TBC complex, a multiprotein complex that acts as a negative regulator of the canonical mTORC1 complex, an evolutionarily conserved central nutrient sensor that stimulates anabolic reactions and macromolecule biosynthesis to promote cellular biomass generation and growth. Within the TSC-TBC complex, TSC2 acts as a GTPase-activating protein (GAP) for the small GTPase RHEB, a direct activator of the protein kinase activity of mTORC1. In absence of nutrients, the TSC-TBC complex inhibits mTORC1, thereby preventing phosphorylation of ribosomal protein S6 kinase (RPS6KB1 and RPS6KB2) and EIF4EBP1 (4E-BP1) by the mTORC1 signaling. The TSC-TBC complex is inactivated in response to nutrients, relieving inhibition of mTORC1. Involved in microtubule-mediated protein transport via its ability to regulate mTORC1 signaling (By similarity). Also stimulates the intrinsic GTPase activity of the Ras-related proteins RAP1A and RAB5 (By similarity).
Synonyms: TSC4; tuberin; LAM; PPP1R160
Tractability: Antibody: UniProt places it where antibodies can reach, with high confidence. PROTAC: UniProt records ubiquitination sites on it; ubiquitination databases record sites on it; its protein half-life has been measured.
Gene: Protein-coding gene on chromosome 16 (2,047,345 to 2,089,491, forward strand). Ensembl gene ENSG00000103197.
Subcellular location: Lysosome membrane; Cytoplasm, cytosol
Subcellular location (Human Protein Atlas): Cytosol
Pathways (Reactome):
Signal Transduction: AKT phosphorylates targets in the cytosol; Energy dependent regulation of mTOR by LKB1-AMPK; Inhibition of TSC complex formation by AKT (PKB)
Autophagy: Macroautophagy
Disease: Constitutive Signaling by AKT1 E17K in Cancer
Vesicle-mediated transport: TBC/RABGAPs
Gene Ontology:
Molecular function: GTPase activator activity; Hsp90 protein binding; phosphatase binding; protein binding; protein homodimerization activity; small GTPase binding
Biological process: anoikis; cellular response to starvation; negative regulation of TOR signaling; negative regulation of TORC1 signaling; positive regulation of macroautophagy; endocytosis; heart development; intracellular protein localization; negative regulation of cell population proliferation; negative regulation of mitophagy; negative regulation of phosphatidylinositol 3-kinase/protein kinase B signal transduction; neural tube closure; positive chemotaxis; protein import into nucleus; regulation of cell cycle; regulation of endocytosis; regulation of insulin receptor signaling pathway; small GTPase-mediated signal transduction; vesicle-mediated transport; regulation of macroautophagy; regulation of small GTPase mediated signal transduction
Cellular component: cytoplasm; cytosol; Golgi apparatus; lysosomal membrane; lysosome; membrane; nucleus; perinuclear region of cytoplasm; postsynaptic density; TSC1-TSC2 complex; synapse
Genetic constraint (gnomAD): Loss-of-function variants: 29 observed, 194.34 expected, observed/expected ratio (o/e) 0.15, 90% interval 0.11 to 0.2. The synonymous counts are far from expectation, so gnomAD's model fits this gene poorly and the ratio says little. Missense variants: 2,429 observed, 2,452.3 expected, observed/expected ratio (o/e) 0.99, 90% interval 0.96 to 1.02. Synonymous variants: 1,349 observed, 1,054.6 expected, observed/expected ratio (o/e) 1.28, 90% interval 1.22 to 1.34.
Cancer hallmarks: proliferative signalling (promotes); escaping programmed cell death; angiogenesis (suppresses); genome instability and mutations (suppresses); escaping immune response to cancer (suppresses); suppression of growth (promotes); escaping programmed cell death (suppresses); change of cellular energetics; escaping immune response to cancer (promotes); invasion and metastasis (suppresses)
Homologues: Orthologues: macaque TSC2 (92% identical), chimpanzee TSC2 (92% identical), mouse Tsc2 (92% identical), rat Tsc2 (91% identical), pig TSC2 (91% identical), guinea pig TSC2 (87% identical), dog TSC2 (86% identical), tropical clawed frog tsc2 (68% identical), rabbit TSC2 (57% identical), zebrafish tsc2 (57% identical), Drosophila melanogaster gig (32% identical). Paralogues in human: RALGAPA1 (18% identical), RALGAPA2 (17% identical).
Diseases named in the same sentence as TSC2 in open-access papers:
TSC2 is named in the same sentence as 354 diseases in open-access papers, as found by Europe PMC text mining. Sharing a sentence is not in itself a finding about the gene and the disease. The quoted sentences say what the papers report.
tuberous sclerosis (394 papers, 2006 to 2026). Hereditary disease characterized by seizures, intellectual disability, developmental delay, and skin and ocular lesions. "Obtaining a precise genetic tuberous sclerosis diagnosis is a challenge as many missense TSC2 variants are variants of uncertain significance (VUS)." (PMID 41648336, 2026). "Variants in TSC2 are associated with Tuberous Sclerosis Complex, a condition characterized by developmental issues and the growth of benign tumors in multiple body parts." (PMID 41522204, 2026). "Two patients had tuberous sclerosis caused by pathogenic variants in the TSC2 gene, and one patient carried a COL4A1 variant predisposing to perinatal hemorrhagic stroke." (PMID 41563000, 2026). "Tuberous sclerosis complex results from loss-of-function mutations in the TSC1 or TSC2 genes, which encode proteins crucial for tumor suppression." (PMID 39901197, 2025). "Tuberous sclerosis complex is a genetic disorder caused by mutations in the TSC1 or TSC2 genes, affecting multiple systems." (PMID 39901197, 2025). "The current understanding of LAM pathogenesis implicates somatic mutations in the TSC2 gene in sporadic LAM, and germline mutations in TSC1 or TSC2 in cases associated with tuberous sclerosis complex." (PMID 40776927, 2025). "The somatic TSC2 variant has been previously reported as a germline variant in individuals with tuberous sclerosis (TSC) and is listed in ClinVar (ID 50087) as “pathogenic” for germline occurrences." (PMID 39859528, 2025). "For over 20 years, significant progress has linked TSC1 or TSC2 gene mutations in stem cells to tuberous sclerosis complex symptoms." (PMID 39901197, 2025). "The known multiple-exon-skipping variant was identified in a patient with tuberous sclerosis complex carrying a large deletion in the TSC2 gene." (PMID 40244027, 2025). "Tuberous sclerosis complex (TSC) is an autosomal dominant genetic disease caused by loss-of-function mutations in the TSC1 or TSC2 genes, which can affect multiple organ systems such as the brain, kidney, and skin." (PMID 40226305, 2025). "Pathogenic variants in TSC2, which encodes the tumor suppressor protein tuberin, are known to cause tuberous sclerosis complex (TSC), an autosomal dominant disorder that affects multiple organs and exhibits a broad range of clinical presentations." (PMID 41358200, 2025). "Genetic testing results indicated no pathogenic or likely pathogenic variants in the coding and surrounding regions of the TSC1 and TSC2 genes, which are linked to tuberous sclerosis and LAM." (PMID 40641534, 2025). "Genetic testing identified a mutationin the TSC2 gene, confirming a diagnosis of tuberous sclerosis complex." (PMID 40822828, 2025). "As the TSC is a key negative regulator of the mTORC1 signaling pathway, loss-of-function mutations in TSC1 or TSC2 lead to the development of various cancers, as well as the tuberous sclerosis complex, characterized by hamartoma formation in multiple tissues." (PMID 40897470, 2025). "Tuberous sclerosis complex is a multisystem genetic disorder caused by variant of TSC1 or TSC2, which were defined as an independent diagnostic criterion for TSC." (PMID 40020127, 2025). "Tuberous sclerosis is mainly caused by TSC1 or TSC2 gene mutation, which leads to a series of clinical manifestations such as enhanced mTOR pathway activity and seizures." (PMID 39539663, 2024). "Tuberous sclerosis a hereditary syndrome that is caused by alterations in the TSC1 (9q34) or TSC2 (16p13.3) genes, and it predisposes patients to several manifestations, including mental retardation, seizures, cardiac rhabdomyomas, and hamartomas." (PMID 38622693, 2024).
tuberous sclerosis (continued). "Genes like SCN1A and TSC2, identified in this study, are associated with syndromes like DS and tuberous sclerosis complex, both featuring epilepsy and developmental impairments." (PMID 39906551, 2024). "Tuberous sclerosis (TS) is a multi‐system, neurodevelopmental disorder caused by heterozygous mutations in either Tsc1 or Tsc2 genes, two negative regulators of mammalian target of rapamycin (mTOR) activity." (PMID 39192595, 2024). "Tuberous sclerosis (TS) is a progressive neurodevelopmental disorder caused by mutations in Tsc1 or Tsc2 genes, leading to hyperactivity of the mTOR pathway." (PMID 39192595, 2024). "Tuberous sclerosis complex is considered to be caused by pathogenic mutations in the TSC complex subunit 1 (TSC1) or TSC2 gene and is unique in the similarity of clinical phenotypes between pathogenic mutations in the two genes." (PMID 36732866, 2023). "Subependymal giant cell tumors are well-known manifestations of tuberous sclerosis caused by alterations in TSC1 or TSC2, and the pathogenic activation of mTOR leads to tumor development." (PMID 37221626, 2023). "TSC1 and TSC2 display an autosomal dominant pattern of inheritance, which means that in a tuberous sclerosis patient, a single pathogenic variant can be considered causative." (PMID 37834053, 2023). "Tuberous sclerosis complex results from inactivating mutations in the TSC1 or TSC2 genes, resulting in hyperactivation of the mTOR signaling pathway, which regulates cell growth, proliferation, survival, and autophagy." (PMID 37232723, 2023). "The genes TSC1 and TSC2 encode tumor suppressors and their loss of function leads to the inherited hamartomas syndrome tuberous sclerosis complex (TSC)." (PMID 36627370, 2023). "Es fand sich eine somatische, trunkierende Mutation des TSC2-Gens („tuberous sclerosis complex“) im Angiomyolipom." (PMID 34605930, 2022). "Human tuberous sclerosis patient-derived neuroepithelial cells carrying TSC2 mutations displayed increased proliferation rate, and mutant cortical neurons developed enlarged soma and altered neurite length." (PMID 35359577, 2022). "Mutations in TSC1 or TSC2 (hamartin and tuberin, respectively) lead to tuberous sclerosis complex, a tumor suppressor syndrome characterized by overgrowth in multiple organs including the brain, resulting in intellectual disability, autism, and epilepsy." (PMID 35250833, 2022). "Tuberous sclerosis complex is characterized by a mutation in TSC1 or TSC2 which activates the signal pathway of mTORC1/RUNX1/EGFR with loss of function." (PMID 36231025, 2022). "Mutations in TSC1 and TSC2 are known to cause syndromic autism, known as tuberous sclerosis, with high rates of comorbid ASD." (PMID 36143905, 2022). "This specific TSC2 splice region is identified as an associated germline variant in tuberous sclerosis syndrome." (PMID 35962345, 2022). "Tuberous Sclerosis Complex (TSC) is caused by loss of function variants in either TSC1 or TSC2 and is characterized by broad phenotypic heterogeneity." (PMID 36793390, 2022). "Among these, the most frequently mutated genes were TSC2 (22 cases), linked to tuberous sclerosis; APC (16 cases), linked to hereditary colon cancer; and the DNA polymerase POLE (16 cases), involved in predisposition to multiple cancers." (PMID 33809641, 2021). "Tuberous sclerosis complex (TSC) is a neurocutaneous disorder caused by germline heterozygous loss-of-function mutations in TSC1 or TSC2." (PMID 34259631, 2021). "Germline mutations in the TSC2 gene leads to an autosomal dominant tumor predisposition syndrome called tuberous sclerosis (TSC), which is characterized by formation of benign tumors in almost every organ in the body." (PMID 34680266, 2021). "Inactivating mutations in either TSC1 or TSC2 cause Tuberous Sclerosis Complex, an autosomal dominant disorder, characterized by multi-system tumor and hamartoma development." (PMID 33891611, 2021).
tuberous sclerosis (continued). "Both human TSC1 and TSC2 are important tumour suppressors, and mutations in them underlie the disease tuberous sclerosis." (PMID 33307091, 2021). "Hyperactivation of mTORC1, through loss-of-function mutations in the genes TSC1 or TSC2, causes the multisystem disorder tuberous sclerosis complex (TSC)." (PMID 34381067, 2021). "TSC2 mutation, epilepsy, early onset, long disease course and high reported seizure frequency (more than once a month), intellectual disability, and tuberous sclerosis–associated neuropsychiatric disorders are risk factors for poor quality of life." (PMID 33225634, 2021). "Alanine substitutions or tuberous sclerosis-associated mutations of H1640, L1641, or N1643 on TSC2, largely impaired the GAP activity (lanes 7–12), to a level comparable to that of lacking TSC complex (lane 2)." (PMID 33436626, 2021). "Tuberous sclerosis (TSC) is an autosomal dominant genetic disorder in which mutation of TSC1 or TSC2 genes leads to increased activation of the mammalian target of rapamycin (MTOR) pathway." (PMID 33897576, 2021). "Heterozygous mutations in either TSC1 or TSC2 that form an MTOR-inhibiting complex can cause tuberous sclerosis by hyperactivating MTOR signaling." (PMID 34200511, 2021). "Case 7 is a girl born at full-term gestation with tuberous sclerosis complex and polycystic kidney disease caused by a deletion in 16p encompassing the TSC2 and PDK1 genes." (PMID 34149382, 2021). "Mutations of TSC1 or TSC2 genes cause tuberous sclerosis, an autosomal dominant genetic disease characterized by the development of histologically diverse hamartomas or benign tumors, including skin, brain, and kidneys." (PMID 33436626, 2021). "Mutations in the mTOR inhibitor genes, TSC1 and TSC2, have been shown to cause overactivity in the mTOR pathway, thus leading to epilepsy in patients with tuberous sclerosis." (PMID 33192961, 2020). "TSC2 have been reported to be associated with tuberous sclerosis, which describe the saturation in some patients with seizures and mental subnormality." (PMID 33287870, 2020). "Mutations in TSC2 are the most common cause of tuberous sclerosis (TSC), a disorder with a high incidence of autism and intellectual disability." (PMID 33054857, 2020). "Tsc1/Tsc2 promotes axonal growth via the upregulation of SAD kinase in tuberous sclerosis complex, which is characterized by tumor predisposition and neurological abnormalities, including epilepsy, mental retardation, and autism." (PMID 32267308, 2020). "Further, the mouse model of Tuberous Sclerosis with Tsc2 loss in Purkinje cells (Tsc2f/−; Cre mice) displays increased marble burying repetitive behavior and Purkinje cell dysfunction, suggesting Purkinje cell loss contribution to ASD phenotype." (PMID 33519379, 2020). "Case 5 identified a heterozygous mutation in TSC2 and was diagnosed as tuberous sclerosis 2(OMIM: 191100)." (PMID 33287870, 2020). "Among these, TSC1 or TSC2 characterizes rare subependymal giant-cell astrocytomas in patients with tuberous sclerosis, causing aberrant activation of mTOR." (PMID 33747896, 2020). "The majority of cases of tuberous sclerosis occur due to pathogenic mutations in TSC2 (encodes for tuberin) whilst TSC1 (encodes for hamartin) and other rare mutations account for remaining cases." (PMID 33409061, 2020). "Only one of ten APEs with TSC1 or TSC2 variants had clinical presentations fitting the diagnostic criteria of tuberous sclerosis complex." (PMID 31875159, 2019). "Four FCD2b cases had a somatic variant in TSC1/TSC2 genes; one FCD2a case had a germline pathogenic variant in TSC2 and was subsequently diagnosed with a mild form of tuberous sclerosis complex." (PMID 31444548, 2019). "A mutation in TSC2 related to tuberous sclerosis causes increased ubiquitination by Phr1 that results in the enhanced degradation of TSC2 by Phr1." (PMID 31438473, 2019).